PALB2 (partner and localizer of BRCA2)
Diseases named in the same sentence as PALB2 in open-access papers (continued):
Sharing a sentence is not in itself a finding about the gene and the disease.
breast cancer (continued). "In this study, we have analysed the prevalence of PALB2 mutations in a cohort of 122 familial breast cancer cases who do not have alterations in BRCA1 or BRCA2 and found 2 (1.3%) were PALB2 carriers." (PMID 23977390, 2013). "It has been suggested that PALB2 contributes to carcinogenesis through haploinsufficiency and/or a dominant negative effect given the paucity of LOH observed in the majority of breast cancer cases from PALB2 carriers, with the exception of one study where a high frequency of LOH was seen." (PMID 23302520, 2013). "Our study proves that PALB2 alterations contribute to the familial but not to the sporadic breast cancer in Poland." (PMID 20122277, 2010). "There are limited prospective data on whether established risk factors modify breast cancer risk in women with pathogenic variants (PV) in BRCA1/2 and virtually no risk modification data for ATM, CHEK2, or PALB2." (PMID 40298171, 2025). "We don’t observe significant differences in the allele frequencies between different regions of Poland, i.e., for BRCA1, PALB2, CHEK2, NBN, RECQL, and also for the GEN1 founder p.Lys645Cysfs*29 variant, neither in breast cancer cases nor in controls (for GEN1 data)." (PMID 40649769, 2025). "Among TNBC stage I-III breast cancers with early (N = 134) and late (N = 66) recurrence, the most frequent alteration was PIK3CA (20.2% vs 33.3%), followed by BRCA1/2 (6.0% vs 9.1%), PD-L1 amplification (2.2% vs 3.0%), PALB2 (1.5% vs 0%), and ESR1 (0% vs 1.5%)." (PMID 40421962, 2025). "Notably, 14% (3/21) of the identified breast cancer affected BRCA1/2 carriers and 25% (4/16) of the PALB2 carriers were diagnosed with another cancer by the time of last follow-up, and four of those were in the female reproductive system (uterus, ovaries, and two cervical cancers)." (PMID 40009290, 2025). "In this study, PALB2 carriers were more often to be detected in patients with HER2-negative breast cancer than non-carriers (83.3% vs. 70.2%), and HR+/HER2- breast cancer was the predominant molecular subtype among PALB2 carriers, accounting for 75%, whereas TNBC accounted for only 8.3%." (PMID 38914840, 2024). "None of the PALB2 carriers were diagnosed with bilateral breast cancer." (PMID 38914840, 2024). "Similarly, early age (≤ 45 years) at breast cancer diagnosis in affected women was not strongly associated with PV carrier status for the non-BRCA genes, particularly for the high-penetrant gene PALB2." (PMID 37084156, 2023). "In addition, the last V5 version of BOADICEA incorporates the effects of pathogenic variants (PVs), not only in BRCA1 and BRCA2 genes, but also in PALB2, CHEK2, ATM and BARD1 for the breast cancer model and RAD51D, RAD51C and BRIP1 for the ovarian cancer model." (PMID 35886069, 2022). "Breast-specific markers as PALB2 or ESR1 were expressed independently of the culture state, although both genes showed a higher relative expression in CTCs from cultured samples (p = 0.03 and 0.06, respectively) suggesting that mammary tumor cells were proliferating in the culture." (PMID 34071445, 2021). "PALB2 and PTEN screening was not routinely offered at the time each of the two patients found to carry a variant in one of these genes (IDs 77 and 225) presented with breast cancer." (PMID 33113089, 2021). "Identification of disease-associated genetic changes in breast cancer susceptibility genes, including BRCA1, BRCA2 and PALB2, not only has actionable implications for carriers, but also for the additional members of their family who are found to carry the high-risk variant." (PMID 33113089, 2021). "Third, TNBC rather than some other tumor subtype as a patient’s first breast cancer diagnosis may be more strongly associated with BRCA2 and PALB2 among AA patients than among EA patients." (PMID 33479248, 2021). "However, the frequencies of these twenty mutant alleles of BRCA1/2, CHEK2, PALB2, NBN, and RECQL have not been measured in a large series of early-onset breast cancer patients from Poland." (PMID 32824581, 2020).
breast cancer (continued). "The family history of PALB2 p.Q775X carrier P36470 also identified in a screen of 564 breast cancer cases not selected for family history appears not to be related to the PALB2 p.Q775X carrier families described based on pedigree inspection, including family F1469 reported in this study." (PMID 23302520, 2013). "The partner and localizer of breast cancer 2 (PALB2) is responsible for facilitating BRCA2-mediated DNA repair by serving as a bridging molecule, acting as the physical and functional link between the breast cancer 1 (BRCA1) and breast cancer 2 (BRCA2) proteins." (PMID 23977390, 2013). "PALB2 H553Q was found in 2 women affected with breast cancer but not in 1,875 controls." (PMID 23977390, 2013). "One possible explanation is that the impact of PGS313 on OS may be confounded by other genetic risk factors, many of which have yet to be identified; several recent papers have found that PGS313 stratifies breast cancer risk in CHEK2, PALB2, and ATM carriers but not BRCA1/2 carriers." (PMID 38704641, 2024). "Although our planned assessment of mammary cancer was not possible due to early-onset neurodegeneration, the results still predict that Atg7 ablation may impair the fitness and survival of Palb2 mutant cancer cells, thereby delaying or preventing tumor development." (PMID 40396054, 2022). "We also observed that breast cancer patients exposed to pesticides had a higher mutational burden when diagnosed before 50 years old (p = 0.00978) and/or when carrying BRCA1 (p = 0.0138), BRCA2 (p = 0.0366), and/or PALB2 (p = 0.00058) variants, a result not found in the unexposed group." (PMID 35875117, 2022). "Regarding breast cancer, in addition to the known high-penetrance pathogenic variants of BRCA1/2, mutations in other high- or intermediate-penetrance genes can increase the risk of cancer and the most common non-BRCA pathogenic or likely pathogenic variants affect PALB2, ATM, and CHEK2 genes." (PMID 33800556, 2021). "Within Asia, a South Korean study of 235 patients at high-risk for hereditary breast cancer and were confirmed not to have a BRCA1/2 mutation were tested with massively parallel sequencing, and 3.6% were found to have pathogenic germline mutations in CHEK2, PALB2, MRE11 and RAD50." (PMID 30093976, 2018). "In contrast, PALB2 mutation carriers were more likely to have ER−HER2− breast cancer (46% in mutation carriers vs. 14% in non-carriers, p = 0.006) and less likely to have ER+HER2− breast cancer (31% in mutation carriers vs. 62% in non-carriers, p = 0.04) compared to mutation-negative women." (PMID 28649662, 2017). "IQGAP1 was specifically upregulated in truncated PALB2 breast IDC compared with the corresponding adjacent noncancerous tissue, similar to results reported for human breast cancer tissues and cell lines." (PMID 40868059, 2025). "BOADICEA V5’s newest version includes the effects of pathogenic variants (PVs), not restricted to BRCA1 and BRCA2 genes but also in PALB2, CHEK2, ATM, and BARD1 for the breast cancer model and RAD51D, RAD51C, and BRIP1 for the ovarian cancer model." (PMID 39590369, 2024). "In this study, we used the latest genetic sequencing technologies to investigate hereditary causes for the second breast cancer in individuals who are known not to have alterations in one of the three main breast cancer genes (BRCA1, BRCA2 and PALB2)." (PMID 36672364, 2023).
breast cancer (continued). "In their study 60% (12/20) of PALB2 and 58% (7/12) of ATM/CHEK2 carriers with breast cancer underwent RRM compared to 57% (4/7) and 29% (2/7) of those without breast cancer, respectively." (PMID 36054727, 2022). "Considering segregation of PALB2 PGVs and CHEK2_1100delC within a family, we detected perfect concordance for PALB2 in FDR with breast cancer but not for CHEK2 with only 7/13 testing positive for the familial variant." (PMID 34113003, 2021). "The fact that the control mice did not develop any mammary tumor while 50% or more of B1p53, P2p53, and B2p53 mice did clearly demonstrate the tumor-suppressive activities of BRCA1, PALB2, and BRCA2 in the mammary gland." (PMID 33893322, 2021). "For women aged 50 years or older at breast cancer diagnosis, RS often exceeded the chemotherapy benefit threshold (≥26) with BRCA1 (71.7% vs 14.4% with none; P <.001), PALB2 (37.1%; P = .001), and BRCA2 (44.3%; P < .001) PVs." (PMID 33426465, 2021). "This is consistent with previous reports in breast cancer and cell line experiments where Signature 3 was only detected for BRCA1/2, PALB2 and RAD51C genes but not ATM or CHEK2." (PMID 33917078, 2021). "Although the genomics features of mouse Brca1 mammary tumors have recently been analyzed by WES30,43, such analyses have not been reported for mouse Brca2 and Palb2 tumors." (PMID 33893322, 2021). "In fact, a recent phase II trial investigating Olaparib in metastatic breast cancer showed an objective response rate of 82% where there was a germline PALB2 PGV; furthermore, 85% of the breast cancers were ER-positive HER2-negative (grade not given)." (PMID 34113003, 2021). "Finally, an analysis of tumours with germline pathogenic variants in six high to moderate breast cancer susceptibility genes did not reveal any significant differences between our cohort and TCGA26, except for a marginally significant higher prevalence in germline PALB2 mutations." (PMID 33353943, 2020). "PALB2 H553Q, predicted to be benign by Polyphen-2 and SIFT, was found in one Malaysian and one Singaporean breast cancer cases (0.1% and 0.2% respectively) and none in the controls." (PMID 23977390, 2013). "To date, no studies have been conducted on breast cancer-driven genes such as ATM, PALB2, CHEK2, and XRCC2 reported from the Khyber Pakhtunkhwa region or Pashtun ethnicity and their potential associations with the various clinicopathologic and hormonal characteristics." (PMID 38784039, 2024). "Statistical adjustments for personal history, type and age of family history, and ancestry using a multivariable logistic regression model further support previous findings that age at breast cancer diagnosis is not a strong predictor of carrying ATM, CHEK2, or PALB2 PVs." (PMID 37084156, 2023).
ovarian carcinoma (205 papers, 2007 to 2026). A malignant neoplasm originating from the surface ovarian epithelium. "Pathogenic coding variants in BRCA1, BRCA2 and PALB2 confer hereditary breast/ovarian cancer risk, yet these regions comprise less than 10% of the genomic footprint of these genes, leaving most sequence unexplored." (PMID 41935071, 2026). "ESMO clinical guidelines affirm that for women carrying PALB2 P/LP variants the risk of ovarian cancer is 3–5% and that for ATM is likely 5%." (PMID 39984762, 2025). "Simultaneously, the updated ACMG guideline highlights that PALB2 variants confer breast and ovarian cancer risks comparable to BRCA1/2 and recommends reporting these variants as secondary findings in clinical exome and genome sequencing." (PMID 40822464, 2025). "Biallelic mutations in PALB2 cause Fanconi anemia, while monoallelic PALB2 mutations are associated with breast and ovarian cancer, carrying an estimated absolute lifetime risk of 41 – 60% and 35%, respectively." (PMID 40800071, 2025). "It is well known that biallelic pathogenic variants in the PALB2 gene result in a subtype of Fanconi anemia, whereas the monoallelic pathogenic variant in PALB2 predisposes carriers to different cancers such as breast, pancreatic, and ovarian cancers." (PMID 38817905, 2024). "RAD51C, RAD51D, BRIP1, and PALB2 are genes known to be associated with a hereditary risk of ovarian cancer." (PMID 39695768, 2024). "Bi-allelic PALB2 germline mutations lead to Fanconi anaemia, whereas mono-allelic PALB2 germline mutations elevate the risk of breast, pancreatic, and ovarian cancer." (PMID 39390525, 2024). "For example, in the French-Canadian founder population, twenty variants in BRCA1, BRCA2, and PALB2 that predispose families to breast and ovarian cancer have been identified at increased frequencies." (PMID 36927983, 2023). "Pathogenic variants in BRCA1/2 are also associated with ovarian cancer risk, as are pathogenic variants in PALB2, RAD51C, and RAD51D." (PMID 36765408, 2023). "More recently, PALB2 has been the subject of functional characterization given its more recent association with hereditary breast and ovarian cancer after its incorporation in early BCa genomic panels." (PMID 36315513, 2022). "New genes (RAD51C, RAD51D, and PALB2) have been identified as increasing susceptibility to ovarian cancer, but further research is required to investigate this." (PMID 35805770, 2022). "Germline PALB2 pathogenic variants are associated with an increased lifetime risk for breast, pancreatic, and ovarian cancer." (PMID 35853885, 2022). "Genomic alterations that involve other genes in HR pathways, including FANCJ/BRIP1 and FANCN/PALB2, have also been suggested to increase the lifetime risk of epithelial ovarian cancer development." (PMID 35330396, 2022). "Germline mutations in HRR genes BRCA1/2 and PALB2 are known to associate with hereditary breast cancer and ovarian cancer, which have also been described in pancreatic cancer and prostate cancer." (PMID 35281878, 2022). "Mutations in BRCA1 and PALB2 were associated with a high risk of ovarian cancer G1 (OR=8.53, p=0.005 and OR=7.03, p=0.03, respectively) and were related to worse all-cause survival for BRCA1 carriers (HR=4.73, 95%CI 1.45–15.43, p=0.01)." (PMID 35313928, 2022). "Mutations in BRCA1 and PALB2 genes were significantly associated with the high risk of ovarian cancer G1, while CHEK2 missense mutation (c.470T>C) was associated with 2-times elevated risk of BOT." (PMID 35313928, 2022). "Mutations of other genes in the Fanconi anemia pathway also confer increased ovarian cancer risk, including PALB2; ATM; RAD51C/D; and BRIP1." (PMID 35159349, 2022). "Recently, we found that pathogenic founder/recurrent germline mutations in 4 genes (BRCA1, BRCA2, RAD51C, PALB2) are responsible for 12.5% of ovarian cancer cases among unselected patients in the Polish population." (PMID 35313928, 2022).
ovarian carcinoma (continued). "We demonstrated that the mutation frequency of PALB2 was 1.6% among high-risk breast and 1% of ovarian cancer patients." (PMID 34439348, 2021). "The mutation screening for PALB2 should be included in the test panel for breast and ovarian cancer patients." (PMID 34439348, 2021). "Based on our data and population data for ovarian cancer incidence in England and Wales in 2016, the cumulative risk of ovarian cancer by age 80 for a carrier of a deleterious PALB2 mutation is 3.2%." (PMID 32546565, 2021). "In 2 studies of 333 unselected and 339 unrelated ovarian cancer cases, the PALB2 mutations were detected in 0.6% of patients." (PMID 33670479, 2021). "In our study we show and confirm that in Poland mutations in RAD51C and PALB2 are associated with ovarian cancer risk." (PMID 33670479, 2021). "The PALB2 mutation was shown to have an increased risk of ovarian cancer with an odds ratio of 4.6 in a European study." (PMID 34439348, 2021). "This is concordant with results of analyses performed on other populations which showed 3–4 times higher frequency of PALB2 mutations in ovarian cancer patients than in controls." (PMID 33670479, 2021). "Heterozygousmutations in PALB2 are known to contribute to the susceptibility of breast and ovarian cancer." (PMID 34092963, 2021). "We found that a pathogenic mutation in BRCA1, BRCA2, RAD51C or PALB2 was found in 12.51% of unselected cases of ovarian cancer in Poland." (PMID 33670479, 2021). "In our analysis recurrent PALB2 mutations were detected in 12 out of 2095 (0.57%) unselected ovarian cancer cases giving the odds ratio of 3.34, but the difference was of borderline statistical significance (95% CI: 1.06–14.6; p = 0.06)." (PMID 33670479, 2021). "Family history is an important aspect to evaluate in this context, however in a recent study only 5 of 21 PALB2 mutation carriers had a family history of breast or ovarian cancer." (PMID 31937788, 2020). "An increased risk of ovarian cancer has recently been confirmed in a study of 976 individuals with protein truncating variants in PALB2 from 524 families, where complex segregation analysis adjusted for ascertainment was performed." (PMID 33086730, 2020). "To date, twenty variants in BRCA1, BRCA2, and PALB2 that predispose families to breast and ovarian cancer have been identified as recurring in the French-Canadian founder population." (PMID 32300229, 2020). "There is also evidence that PALB2 silencing by mutation and DNA hypermethylation predisposes individuals to ovarian cancer." (PMID 36046263, 2020). "Initial analysis of 3227 EOC cases and 3444 matched-controls suggested that larger numbers of samples were required to determine if PALB2 was an ovarian cancer susceptibility gene (p 0.08)." (PMID 33086730, 2020). "More than half (8/15; 53.3%) of our cases were mutation carriers of genes for Fanconi anemia, and among the genes, BRCA2 and PALB2 are known to be associated with other cancers, including breast and ovarian cancers." (PMID 30840646, 2019). "Genetic testing for disease-causing mutations in BRCA1, BRCA2, PALB2, and other BC susceptibility genes is strongly recommended for people with a BC and/or ovarian cancer family history." (PMID 30940775, 2019). "This study aimed to apply massively parallel sequencing to characterise the mutation spectrum of PALB2 in women from South-West Poland and West Ukraine affected with breast or ovarian cancer." (PMID 29052111, 2018). "The purpose of this study was to characterise the spectrum of PALB2 mutations in women affected with breast or ovarian cancer from South-West Poland and West Ukraine." (PMID 29052111, 2018). "Germline mutations in the PALB2 gene were observed at a frequency of approximately 1.5% in Polish breast and/or ovarian cancer patients." (PMID 28279176, 2017). "The PALB2 gene mutation rate (1.5%) determined for our group of breast and/or ovarian cancer patients was similar to those reported by other studies." (PMID 28279176, 2017).